TNF (tumor necrosis factor)
Diseases named in the same sentence as TNF in open-access papers (continued):
Sharing a sentence is not in itself a finding about the gene and the disease.
psoriasis (continued). "In a study on primary human keratinocytes, it was shown that TNF-α, a prominent cytokine in the pathogenesis of psoriasis, induces H2O2 production in vitro and that this effect is dose-dependent, which is consistent with studies on other human cell types." (PMID 35883760, 2022). "Biological therapies such as tumor necrosis factor (TNF), interleukin (IL) 12/23 and IL-17 inhibitors have revolutionized the management of moderate-to-severe psoriasis allowing many patients to attain clear skin." (PMID 35566756, 2022). "For PASI75, secukinumab and ustekinumab had the highest RR, whereas the TNF inhibitor adalimumab had the lowest RR in studies with pediatric psoriasis." (PMID 36226155, 2022). "These genetic associations also provided biological insight for how TNF-α inhibitor treatment, suggesting the existence of different biological mechanisms through which TNF-α inhibitors exert their immunomodulatory role in psoriasis." (PMID 36059983, 2022). "Almost twenty years ago, monoclonal antibodies or fusion proteins selectively blocking Tumor Necrosis Factor alpha (TNFα) have strikingly improved the therapeutic response of psoriasis." (PMID 36614836, 2022). "Patients with secukinumab or ustekinumab as index drug had the lowest frequency of switch to other PSObio drugs; however, it should be noted that these groups are also the least numerous, as these drugs were approved for psoriasis later than anti-TNF drugs." (PMID 35682382, 2022). "Catalpol-induced SIRT1 up-regulation decreased oxidative stress and pro-inflammatory mediators by suppressing NF-κB and MAPKs signaling pathways in both imiquimod (IMQ)-induced psoriasis-like mice and TNF-α-stimulated human keratinocytes, HaCat, cells." (PMID 35883477, 2022). "Modern biological therapies, such as TNF-α, IL-12 family, and IL-17 inhibitors, are intended to profoundly reshape the cytokine configuration of patients with inflammatory diseases such as psoriasis, with tremendous success in disease control." (PMID 35563587, 2022). "For a long time, psoriasis was believed to be initiated by the release of TNF alpha, interferon (IFN)-alpha and IFN-beta from plasmacytoid dendritic cells (DCs)." (PMID 36532043, 2022). "Macrophages play an important role in psoriasis pathogenesis since they are activated by pro-inflammatory cytokines and release TNFα and IL-23 and exacerbate inflammation even more." (PMID 36226313, 2022). "The levels of inflammatory TH17 cytokines (IL-17A, IL-22 and IL-23) and TH1 cytokines (IL-1β, IFN-γ and TNF-α) were also measured in the skin; psoriasis is considered to be regulated by TH17 and TH1 responses." (PMID 35562873, 2022). "The hypothesis of cardiovascular risk reduction in psoriasis patients receiving ustekinumab was further questioned by the observation of no substantially different risk of major adverse cardiovascular events among TNF-a inhibitors, ustekinumab or placebo therapy in several studies." (PMID 35755028, 2022). "In psoriasis, IL-17 can activate macrophages to express TNF-α and IL-1β, thereby inducing fibroblast activation." (PMID 35878202, 2022). "The cigarette smoking-induced COPD model showed increased key cytokines in psoriasis patients, such as TNF-α and IL-17." (PMID 35457278, 2022). "Adalimumab and etanercept, other TNF-α antagonists, improved depression scores in patients with rheumatic (i.e., ankylosing spondylitis), Crohn’s disease, psoriasis or hidradenitis suppurativa and comorbid depressive symptoms." (PMID 36291336, 2022). "CXCL1 is one of the factors involved in the inflammatory responses that are responsible for skin lesions in psoriasis; other factors include the IL-23→Th17 cells axis, TNF-α and interferon-γ (IFN-γ)." (PMID 36613652, 2022). "In the past decades, innovative approaches including biological agents have emerged and been wildly applied, such as TNF-α inhibitors that have been approved in China for the treatment of psoriasis." (PMID 36033390, 2022).
psoriasis (continued). "We managed to find a few articles describing beneficial effects on the course of NDs in patients receiving anti-TNFα agents for psoriasis." (PMID 36226313, 2022). "The available biologics for psoriasis basically target the function of TNF-α, IL-17A orIL-12/23 includes etanercept (anti-TNF receptor fusion protein), adalimumab and infliximab (anti-TNFα antibodies), anti-IL-17(receptor) molecules and ustekinumab." (PMID 36518145, 2022). "Elevated expression of M1-Mø is another key characteristic of psoriasis, it has been found that various inflammatory cytokines such as ILs and TNF-α secreted by M1-Mø contribute to psoriasis by triggering inflammation in keratinocytes." (PMID 36467042, 2022). "The expression of TNF-α and IL-6 as well as IL-22, IL-23, and IL-17 family of cytokines (IL-17A, IL-17E, and IL-17F) was significantly increased in psoriasis skin lesions." (PMID 35663991, 2022). "Biologic agents for psoriasis treatment include tumour necrosis factor α (TNF-α) inhibitors, interleukin (IL)-23 inhibitors, IL-12/23 inhibitors, or IL-17 inhibitors." (PMID 36013015, 2022). "The patients with idiopathic psoriasis (mean age ± SD, 56.15 ± 13.76 years) were slightly older than patients with anti-TNF-induced PPP (49.17 ± 11.11 years)." (PMID 36143237, 2022). "The cytokine TNF-α is a well-known pathogenetic mediator of many immune-mediated diseases, including psoriasis, targeted by the first biological drugs, such as etanercept and infliximab." (PMID 36364420, 2022). "TNF-α inhibitors were the first biologics to obtain marketing authorization and reimbursement for psoriasis, and they include etanercept (ETN), infliximab (INF), and adalimumab (ADA)." (PMID 35329831, 2022). "TNF inhibitors are also currently used in psoriasis and are effective in the skin manifestation of PsA." (PMID 36430392, 2022). "Coptisine reduced the severity of psoriasis-like skin lesions, decreased epidermal hyperplasia and the levels of inflammatory cytokines TNF-α, IL-17, and IL-22." (PMID 35209199, 2022). "Studies have shown that CXCL16 has chemotactic effects on CD4+ T cells, and further activates CD8+ T cells, thereby promoting the secretion of IFN-γ, IL-17 and TNF-α, etc., and is involved in the pathogenesis of psoriasis progress." (PMID 35693833, 2022). "The levels of chemokines such as CXCL8 and CCL20 were dramatically increased in the TNF-α/IL-17/IFN-γ-induced HaCaT psoriasis model." (PMID 36015080, 2022). "Tumor necrosis factor antagonists' effectiveness in treating psoriasis is probably due to the impacts that indirectly affect interleukin-23/T17 signaling." (PMID 36106203, 2022). "TNF-α is another inflammatory cytokine that was reported to regulate RA, psoriasis and inflammatory bowl disease." (PMID 35937499, 2022). "Approaches in psoriasis therapy are mainly focused on inhibiting immune signaling such as TNF-α, IL-17, IL-12/IL-23, BTK, and other tyrosine kinases." (PMID 36620087, 2022). "Fourth, pipelines on biosimilars of TNF-α were another hotspot in the drug for psoriasis accounting for 36% (17/47) due to the patent expiration of adalimumab." (PMID 35529441, 2022). "Biologics that block the signaling of TNF-, IL-17, and IL-12/IL-23, for instance, are often utilized in psoriasis patients." (PMID 36556472, 2022). "The expression of CTACK would be upregulated with the stimulation of TNF-α and IL-1β and be reduced cutaneously during the administration of etanercept in psoriasis patients." (PMID 36741410, 2022). "To assess the potential preclinical benefit of R. mucosa in psoriasis we assessed for direct effects on surface TNF signaling in cell cultures and identified direct effects on the TNF axis." (PMID 36605199, 2022). "The TNF inhibitor treatment showed lower hazard ratios of myocardial infarction (HR = 0.50, psoriasis patient n = 8845) and stroke (incidence rate = 0.30, psoriasis patient n = 72,373) (a large cohort study)." (PMID 35457278, 2022).
psoriasis (continued). "Japanese guidance for the use of biologics for psoriasis recommends starting treatment with TNF inhibitors from an early stage for patients with psoriatic arthritis to prevent the progression of joint destruction." (PMID 35799412, 2022). "Psoriasis is an autoimmune inflammatory disease characterized by cytokines elevated, including TNF-α, IL-1β, IL-6, and IL-17A." (PMID 35860030, 2022). "It is at this moment proven that those molecules can reverse clinical, histologic, and molecular features of psoriasis, superior to TNF-alpha inhibitors." (PMID 35563587, 2022). "Cross-talk between the innate and adaptive immune systems mediated by tumor necrosis factor-alpha (TNF-α) and interferon-gamma (IFN-γ) has also been implicated in the pathogenesis of psoriasis." (PMID 35805960, 2022). "Nine (2%) patients had history of psoriasis and four (0.9%) patients had history of uveitis before anti-TNF initiation." (PMID 35091460, 2022). "Studies have shown that both IFN-γ and TNF-α cytokines are increased in the serum of patients with psoriasis and their respective receptors are increased in atherosclerosis." (PMID 35514987, 2022). "This study included 39 patients with different patterns of psoriasis and lesions from six patients with anti-TNF-induced PPP." (PMID 36143237, 2022). "Patients with moderate to severe psoriasis who require systemic treatment during the pandemic can safely resort to TNF alpha inhibitors." (PMID 35566548, 2022). "One of the sources of IL-17A in psoriasis is Th17 cells, then they are stimulated to secrete further cytokines by IL-23, which include (besides IL-17A): IL-17F, IL-21, IL-22, IL-26, and TNF-α." (PMID 36226313, 2022). "Lifestyle habits, such as smoking, negatively impact the course of psoriasis through the production of free radicals that activate the tumor necrosis factor (TNF)‐alfa and Janus kinase (JAK) pathways." (PMID 35156278, 2022). "Based on the findings of inflammatory cascades involved in the onset and maintenance of psoriasis, a wide range of biological therapies are currently licensed that target TNFα, IL-12/23, IL-17, and IL-17 receptor." (PMID 35742957, 2022). "Statins have been reported to significantly reduce TNF-α levels, opening a new path in psoriasis treatment." (PMID 36035406, 2022). "As these agents target upstream cytokine involved in the psoriasis pathogenesis, dosing interval of longer duration is an advantage as compared to the downstream cytokines such as IL-17 and TNF-α." (PMID 35265634, 2022). "Due to the shared pathology of TNF and ceramide family lipids, we thus aimed to assess if R. mucosa directly influences the TNF axis in vitro and models of psoriasis in vivo." (PMID 36605199, 2022). "In recent years, newly developed biological agents such as IL-23 inhibitors and TNF-α inhibitors seem to have brought new hope to patients with severe psoriasis, but the high treatment cost or some adverse reactions limit the widespread use of these drug." (PMID 36035406, 2022). "TNF-α acts as the main mediator during the initiation phase of classical psoriasis and can sustain the disease over the long term." (PMID 35203707, 2022). "Stimulating cells of the TNF-α HaCaT line and then incubating with curcumin can inhibit TNF’s anti-apoptotic effect, that is, stopping the further development of psoriasis." (PMID 35163855, 2022). "Multiple biologics targeting TNF-α, IL-23, and IL-17 have shown tremendous success in the treatment of psoriasis." (PMID 35075118, 2022). "A total of 43 patients with psoriasis (19 patients treated with TNF-α mab and acitretin, 24 patients treated with acitretin only) and 24 normal controls were included in this study." (PMID 35814239, 2022). "TNF-α is elevated in psoriasis and increases proatherogenic small dense LDL and ox-LDL levels while lowering HDL concentrations." (PMID 36012327, 2022).
psoriasis (continued). "A good response to adalimumab was observed in patients previously treated with other biological drugs for psoriasis, including other anti-TNF drugs." (PMID 35682382, 2022). "Murine studies demonstrated that depletion of macrophages improved psoriasis inflammation and reduced the levels of Th1 cytokines, including IL-1α, IL-6, IL-23 and TNF-α to normal levels." (PMID 35837394, 2022). "Among them, the p38 MAPK signaling pathway is the most closely related to the development of progression of psoriasis, which can promote the secretion of inflammatory cytokines (e.g, IL-6, IL-1β, and TNF-α) to accelerate the progression of psoriasis." (PMID 36618400, 2022). "The clinical characteristics of TNF-α inhibitor-induced psoriasiform eruptions include a higher frequency of palmoplantar involvement compared with classical psoriasis." (PMID 35884790, 2022). "Ten articles were selected to evaluate the difference in psoriasis development between CD and UC patients who had anti-TNF therapy." (PMID 35801760, 2022). "With the development of the pathogenesis of psoriasis, the role of IL-17, IL-23, CXCL16, CXCL17 and tumor necrosis factor-α (TNF-α) in the immunoinflammatory process of psoriasis is becoming clear." (PMID 35693833, 2022). "The inflammatory cytokines, such as interleukin IL-12, IL-17, IL-23, and tumor necrosis factor TNF-α are elevated in the peripheral blood of patients with psoriasis." (PMID 36249714, 2022). "Recently developed biologic therapies that target not only the IL-23-Th17-IL-17 axis but the TNF-α-signaling as well, exhibit high efficacy and safety in patients with psoriasis." (PMID 35925616, 2022). "Biological therapies such as tumour necrosis factor (TNF), interleukin (IL) 12/23 and IL-17 and IL-23 inhibitors have revolutionised the treatment of moderate-to-severe psoriasis allowing many patients to achieve complete remission." (PMID 36013015, 2022). "To do so, we used the Phenion full-thickness reconstructed skin model to apply epidermally two different biological factors already used to treat patients with psoriasis, namely, anti-TNFα and anti-IL-17α." (PMID 35742957, 2022). "Patients with ulcerative colitis and Crohn disease were compared with determine the differences in anti-TNF-induced psoriasis." (PMID 35801760, 2022). "In recent years, various biologics targeting specific inflammatory cytokines, such as IL-17A inhibitors, TNF-α inhibitors, IL-23 inhibitors, etc., have also been shown to be effective in treating psoriasis." (PMID 36467042, 2022). "In this large cohort study, involving 242 psoriasis patients, dermal patch biomarker patches were applied before and after 12 weeks of drug treatment with IL-23, IL-17, and TNF-α." (PMID 35682804, 2022). "Leptin promotes IL-1, IL-6 and TNF-α production through its proinflammatory activity, which also affects psoriasis." (PMID 35216228, 2022). "Biologic therapies currently approved for moderate-to-severe psoriasis includes agents targeting TNF-alpha, IL-17, the p40 subunit of IL-12 and IL-23, and the p19 subunit of IL-23." (PMID 36615129, 2022). "And 7 articles were used to compare the psoriasis development according to the types of anti-TNF agents." (PMID 35801760, 2022). "For PASI90, ixekizumab and secukinumab had the highest RR, whereas the TNF inhibitor etanercept had the lowest RR in studies with pediatric psoriasis." (PMID 36226155, 2022). "In order to gain a better knowledge of miRNAs role in the disease, the current study looked into the influence of miR-203 expression and its target genes SOCS3, SOCS6, TP63, TNF-α, IL-8, and IL-24 on the pathogenesis and clinical course of psoriasis." (PMID 36341243, 2022). "SAE incidences with biologics were low (up to 3%) in investigated pediatric and adult psoriasis RCTs, except for a pediatric study arm with the TNF inhibitor adalimumab (8%)." (PMID 36226155, 2022).
psoriasis (continued). "According to the data from documents, a 7.5 ng/mL concentration of TNF-α was adopted to establish psoriasis-like cell models in our experiment." (PMID 36178125, 2022). "The abnormal production of inflammatory cytokines, such as TNF-α, IL-6, IL-17 and IL-23, are confirmed to play key roles in psoriasis.The protein level of IARS was up-regulated in NHEKs treated with TNF-α, IL-6, IL-17 and IL-23." (PMID 36419191, 2022). "A mixture of five inflammatory molecules (TNF-α, IL-1α, IL-17A, IL-22, and oncostatin M; 10 ng/mL each) was used to stimulate HaCaT cells to mimic the microenvironment of psoriasis." (PMID 35209199, 2022). "TNF-mediated chronic inflammation by controlling innate and adaptive immune cells and induced diverse chronic inflammatory diseases, such as psoriasis." (PMID 35277199, 2022). "Network pharmacological analysis revealed that RPE components target 20 genes that are linked to psoriasis-related pathways, such as IL-17, MAPK, and TNF signaling pathways." (PMID 36555642, 2022). "The prevalence of NAFLD in psoriasis patients is high and related to a higher prevalence of MetS, bacterial translocation, and a higher pro-inflammatory state (TNF-α, TGF-β level, and bacterial translocation)." (PMID 35757712, 2022). "The therapeutic efficacy of anti-TNF-α/IL-23/IL-17A biologics for psoriasis suggests that the TNF-α/IL-23/IL-17A axis plays a central role in its pathogenesis." (PMID 35663970, 2022). "In summary, from a posttreatment point of view, these data identified IL-17A and TNF-α as critical molecules that maintain psoriasis plaques." (PMID 36483564, 2022). "Blocking the free-bound and trans-membranous TNF-α in psoriasis from binding to a TNFR2 receptor can neutralize this overproduced cytokine." (PMID 35203707, 2022). "At the same time, EAHM showed a superior or similar level of an effect to CM on the inflammatory findings of psoriasis in indicators such as IL-17, IL-23, and TNF-α, and also showed positive results on the quality of life in psoriasis." (PMID 35745164, 2022). "The main pathogenesis of psoriasis highlighted the crosstalk between the innate and adaptive immune system, the central role of IL-23 and helper T cell type 17 responses, the role of TNFα and interferons, and the link to genetics." (PMID 36106326, 2022). "The biological therapies targeting the inflammatory cytokines such as tumor necrosis factor (TNF)-α and interleukins (ILs)-12/23/17 have shown good efficacy, which have been the first-line systemic treatment for psoriasis in many national guidelines." (PMID 35814239, 2022). "We found that the mRNA and pro-/mature protein levels of IL-1β, another important cytokine in psoriasis, were significantly increased after stimulation with IL-17A and TNF-α." (PMID 35153790, 2022). "Th17 cells in psoriasis process release different cytokines such as IL-17, IL-22 and tumor necrosis factor -α and participate in the process of macrophage stimulation of dendritic cells (DC) to spread inflammatory response." (PMID 36591241, 2022). "In fact, applying both anti-TNFα and anti-IL-17α resulted in a significant decrease in epidermal thickness which in the context of psoriasis would be a desirable effect." (PMID 35742957, 2022). "Higher caspase-1 and IL-1β levels has been observed in patients with psoriasis that normalized after treatment with TNF-α." (PMID 35265634, 2022). "For example, a Spanish experimental study reported decreased peripheral microvascular resistance in psoriasis patients (nailfold vessel resistance index) following a 52-week TNF-alpha inhibitor administration (adalimumab)." (PMID 35883760, 2022). "Increased IL-33 serum levels have been found in patients with psoriasis, and they were significantly reduced after treatment with TNF inhibitors." (PMID 36012744, 2022). "First, we identified the occurrence of psoriasis in patients with IBD after anti-TNF treatment in 7 studies." (PMID 35801760, 2022).